COL4A3 (collagen type IV alpha 3 chain)
Diseases named in the same sentence as COL4A3 in open-access papers (continued):
Sharing a sentence is not in itself a finding about the gene and the disease.
Alport syndrome (continued). "Alport syndrome (AS) is a rare monogenic hereditary disorder caused by mutations in any of the type IV collagen genes COL4A3, COL4A4 (2q36.3 both) and COL4A5 (Xq22.3)." (PMID 34681722, 2021). "The situation is more complicated in recessive Alport syndrome by the requirement for two COL4A3 or COL4A4 variants in trans." (PMID 33854215, 2021). "Alport syndrome (AS), which is a rare hereditary disease caused by mutations of genes including COL4A3, COL4A4 and COL4A5, has a wide spectrum of phenotypes." (PMID 34774011, 2021). "In 677 patients with a priori clinical diagnosis of GN, pathogenic variants in COL4A5, COL4A3 or COL4A4 were detected confirming the diagnosis of Alport syndrome or TBMN." (PMID 36939782, 2021). "In autosomal recessive Alport syndrome (ARAS) with variants in the COL4A3 or COL4A4 genes, female and male patients are equally affected and also reach ESRD early in life." (PMID 34209341, 2021). "Alport syndrome (AS) is an inherited renal disease caused by variants in COL4A3, COL4A4, or COL4A5 gene." (PMID 34209341, 2021). "Many women with X-linked Alport syndrome, and males and females with heterozygous COL4A3 or COL4A4 variants, or sometimes digenic COL4A3 and COL4A4 variants, have only microscopic haematuria." (PMID 33854215, 2021). "High-throughput next-generation sequencing (NGS) technology can improve the diagnosis of Alport syndrome by providing molecular confirmation of COL4A3, COL4A4, or COL4A5 mutations." (PMID 34238373, 2021). "Autosomal recessive Alport syndrome (ARAS) is caused by pathogenic variants in both alleles of either COL4A3 or COL4A4 genes." (PMID 33772369, 2021). "With the rapid development of molecular genetic testing, Alport syndrome causes have been restricted mostly to variants in the COL4A5 or COL4A3/COL4A4 genes." (PMID 34238373, 2021). "COL4A3 mutations are associated with several phenotypes, such as Alport syndrome that associates renal failure, variable HL (which can be of late onset) and ocular involvement, including cataract and retinopathies." (PMID 34440452, 2021). "Alport syndrome is a genetic and hereditary disease, caused by mutations in the type IV collagen genes COL4A3, COL4A4 and COL4A5, that affects the glomerular basement membrane of the kidney." (PMID 34681722, 2021). "Alport syndrome (AS) is a hereditary type IV collagen disorder resulting from the mutations in the gene COL4A3/4/5, which encodes α3/α4/α5 type IV collagen chains, with primary defects in postnatal maturation of glomerular basement membrane (GBM)." (PMID 32098220, 2020). "Mutations in COL4A3/4/5 genes occur during the early stage of the fertilized ovum and persist throughout life in Alport syndrome patients." (PMID 32117450, 2020). "Alport syndrome is caused by mutations in the genes COL4A3, COL4A4 or COL4A5 and is characterised by progressive glomerular disease, sensorineural hearing loss and ocular defects." (PMID 31044288, 2020). "Alport syndrome is a hereditary progressive chronic kidney disease caused by mutations in type IV collagen genes COL4A3/4/5." (PMID 32117450, 2020). "Both thin basement membrane nephropathy (TBMN) and autosomal dominant Alport syndrome (ADAS) are types of hereditary nephritis resulting from heterozygous mutations in COL4A3 or COL4A4 genes." (PMID 32232700, 2020). "Here, we report compound mutations of the COL4A3 gene including a novel allele identified in a patient with Alport syndrome." (PMID 33524082, 2020). "Their maintenance, regeneration and remodeling have been extensively studied in normal kidney physiology as well as renal diseases, such as X-linked and autosomal recessive Alport syndrome carrying genetic mutations in COL4A3, COL4A4 or COL4A5 gene." (PMID 32210336, 2020). "If every person with a heterozygous COL4A3 or COL4A4 mutation were labelled with the diagnosis of Alport syndrome, its incidence would increase from the current level of 1 in 5–10,000 to as high as 1 in 100, with ESKD being uncommon." (PMID 31044288, 2020).
Alport syndrome (continued). "Alport syndrome is caused by mutations in the COL4A3 (OMIM, # 120070), COL4A4 (OMIM, # 120131), or COL4A5 (OMIM, # 303630) genes encoding collagen IVα3, α4, and α5 chains." (PMID 30883042, 2019). "Alport Syndrome (AS) is a clinically and genetically heterogeneous, progressive nephropathy caused by mutations in COL4A3, COL4A4, and COL4A5, which encode type IV collagen (Gubler, 2008; Hudson, Tryggvason, Sundaramoorthy, & Neilson, 2003)." (PMID 30968591, 2019). "A single mutation in the COL4A4 gene was detected in three male and 10 female patients, a single COL4A3 gene mutation was detected in two male and two female patients, and X-linked Alport syndrome (COL4A5 gene mutation) was detected in four male patients." (PMID 30805210, 2019). "About 1% of patients diagnosed or suspected for Alport syndrome had mutations in more than one of the COL4A3‐5 genes." (PMID 30883042, 2019). "The COL4A3 gene encodes α3 chains, and it is concluded that pathogenic COL4A3 mutations account for Alport syndrome (AS)." (PMID 30881523, 2019). "Patients with XLAS who also had heterozygous pathogenic COL4A3 or COL4A4 variants accounted for 1% of Alport syndrome." (PMID 30883042, 2019). "Homozygous or hemizygous mutations in glomerular filtration barrier genes, such as the COL4A3/4/5 genes, result in Alport syndrome (AS), while homozygous mutations in the NPHS1 and NPHS2 genes result in congenital nephrotic syndrome." (PMID 30691124, 2019). "Alport syndrome is an inherited renal disease caused by mutations in COL4A3, COL4A4, or COL4A5 genes." (PMID 30883042, 2019). "COL4A3 is an important risk gene for HAPC that is also linked to many diseases such as the Alport syndrome, focal segmental glomerulosclerosis, and type 2 diabetes." (PMID 30053909, 2018). "In the current study, we apply this scanning HIM technique to examine glomerular abnormalities in the collagen type IV α3 chain (Col4a3) deficient mice that model Alport syndrome." (PMID 28916834, 2017). "Alport syndrome (AS) is a clinically and genetically heterogeneous, progressive nephropathy caused by mutations in COL4A3, COL4A4, and COL4A5, which encode type IV collagen." (PMID 28542346, 2017). "Alport syndrome (AS) is an inherited progressive renal disease caused by mutations in COL4A3, COL4A4, and COL4A5 genes." (PMID 28570636, 2017). "There are occasional reports of individuals with two COL4A5 mutations, and others with autosomal recessive Alport syndrome and mutations in both COL4A3 and COL4A4 with a later age at onset of renal failure." (PMID 27627812, 2016). "Twenty COL4A3 or COL4A4 mutations were identified in the LOVD databases in individuals diagnosed clinically with autosomal dominant Alport syndrome." (PMID 27627812, 2016). "Col4a3-deficient (Col4a3KO) mice, one of murine models of Alport syndrome, are developed by gene targeting at the Col4A3 locus and raised on a 129/SvJ genetic background." (PMID 26555339, 2015). "In humans, defects in the COL4A3/COL4A4/COL4A5 complex are the major cause of Alport syndrome, which is associated with a loss of BM integrity." (PMID 26451951, 2015). "Patients from two families that segregated mutations COL4A3-c.2621–2622delGAinsT and COL4A3-p.(G1077D) were married and had children who inherited both mutations and manifested classical autosomal recessive Alport Syndrome." (PMID 25514610, 2014). "We therefore analyzed a mouse model of autosomal recessive Alport syndrome that lacks the collagen α3α4α5(IV) network due to a Col4a3 null mutation." (PMID 24137544, 2013). "Sequencing of these candidate genes most likely associated with kidney defects and proteinuria revealed 2 mutations in COL4A3 gene, a gene associated with Alport syndrome and SALL2, a gene associated with urinary tract development." (PMID 24130771, 2013). "Pedigree analysis confirmed that the COL4A3 mutations were compound heterozygous and subsequent clinical work-up confirmed dual disease, Alport syndrome and VUR." (PMID 24130771, 2013).
Alport syndrome (continued). "Alport syndrome is associated with three genes: COL4A5 with the X-linked form (MIM 301050) while COL4A3 and COL4A4 are associated with the autosomal-recessive form (MIM 203780)." (PMID 23398688, 2013). "Because the human COL4A3 gene is causative for Alport syndrome, a mouse knockout for Col4a3 was generated." (PMID 22567353, 2011). "A complex binding site for ZEB1 protein exists in the promoter of a collagen gene, COL4A3, which is linked to the autosomal recessive form of Alport syndrome." (PMID 19997581, 2009). "However, Alport syndrome caused by COL4A3 and COL4A4 changes should always be regarded as potentially serious." (PMID 40806767, 2025). "Alport syndrome is a genetic condition characterized by kidney disease, loss of hearing, and eye abnormalities, due to a mutation in the genes encoding alpha-3, alpha-4, and alpha-5 of type IV collagen (COL4A3, COL4A4, COL4A5) or collagen 4 α345 network." (PMID 41299396, 2025). "Alport Syndrome was the most frequent disorder, with COL4A3 and COL4A5 mutations predominating." (PMID 41288877, 2025). "For example, in Alport syndrome, a hereditary kidney disorder, where a previously reported synonymous variant located in exon 13 of COL4A3 (p.Thr255Thr) was recently shown to alter splicing and induce skipping of exon 13, resulting in a truncated COL4A3 protein product." (PMID 41278537, 2025). "All patients clinically diagnosed with Alport syndrome also exhibited extrarenal manifestations, including sensorineural hearing loss, consistent with syndromic features of AS and supporting the pathogenic relevance of identified COL4A3 and COL4A5 variants." (PMID 41288877, 2025). "The precise prevalence of Alport syndrome in the US is uncertain, but estimates of the prevalence of heterozygous pathogenic variants in these genes are ~1 in 100 individuals for either COL4A3 or COL4A4, and ~1 in 2000 individuals for hemizygous or heterozygous variants in COL4A5." (PMID 40317772, 2025). "According to the literature, on its own, it may be associated with a normal urinary sediment, proteinuria, and focal segmental glomerulosclerosis or, in association with another COL4A3 variant, with autosomal recessive Alport syndrome and kidney impairment." (PMID 40004525, 2025). "Alport syndrome (AS), also known as hereditary nephritis, is a genetically and phenotypically heterogeneous disease caused by mutations in genes encoding type IV collagen, specifically the alpha-3, alpha-4, and alpha-5 chains (COL4A3, COL4A4, COL4A5)." (PMID 39981328, 2025). "Mutations and variants of COL4A3 contribute to Alport syndrome and DKD." (PMID 38926794, 2024). "Alport syndrome is a rare genetic kidney disease caused by variants in the COL4A3/A4/A5 genes." (PMID 39424670, 2024). "Following a genetic test, the results may indicate a genetic variant in one of the Alport syndrome genes (COL4A3, COL4A4, or COL4A5)." (PMID 38745975, 2024). "Heterozygous variants in COL4A3 or COL4A4 cause autosomal dominant Alport syndrome." (PMID 38765603, 2024). "While systemic loss of Col4a3 in Col4a3KO mice recapitulates the GBM defects associated with Alport syndrome, the precise cellular contribution of type IV collagen chains in the GBM remains unknown." (PMID 38561223, 2024). "Extensive screening of 2017 unrelated Ashkenazi Jews yielded a carrier frequency of 1 in 183, indicating that COL4A3 c.40_63del is a founder variant and may be an important cause of Alport syndrome in this population." (PMID 37895203, 2023). "Thus for a woman with a single or heterozygous pathogenic missense variant in the COL4A3 gene: a single copy of this variant is consistent with the diagnosis of AD Alport syndrome; and two copies with AR Alport syndrome." (PMID 37342499, 2023).
Alport syndrome (continued). "Numerous studies have confirmed that mutations in different subtypes of Col4A3, A4, and A5 can lead to Col4-associated glomerulopathy (Bárbara Tazón Vega, 2003), including Alport syndrome (AS), thin basement membrane nephropathy (TBMN), and focal segmental glomerulosclerosis (FSGS)." (PMID 37323683, 2023). "However, mutations in COL4A3-5 genes are known to cause Alport’s syndrome, which manifests as progressive sensorineural hearing loss and nephritis." (PMID 36653343, 2023). "Moreover, heterozygous mutations of COL4A3 or COL4A4 are reported to cause autosomal dominant Alport syndrome (ADAS)." (PMID 36292665, 2022). "On its own it may be associated with a normal urinary sediment, proteinuria and FSGS or in association with another COL4A3 variant, with AR Alport syndrome, and kidney failure." (PMID 35602506, 2022). "Thus, the new classification of Alport syndrome by “the Alport Syndrome Classification Working Group” published in 2018 can help to minimize diagnostic confusion of disorders arising from the COL4A3 or COL4A4 genes." (PMID 33772369, 2021). "COL4A3 gene variants have been reported to be involved in the occurrence and development of various diseases, such as diabetic nephropathy, focal segmental glomerulosclerosis, and Alport syndrome." (PMID 34593020, 2021). "Heterozygous mutation in the COL4A3 gene responsible for autosomal dominant Alport syndrome might also generate isolated HL or HL with ocular involvement in some carriers." (PMID 34440452, 2021). "Occurrence of Alport syndrome is caused by mutations in COL4A3, COL4A4, or COL4A55." (PMID 34675305, 2021). "Some congress participants subscribed to the view that anyone with a heterozygous COL4A3 or COL4A4 mutation should be diagnosed with Alport syndrome, to ensure that the significance of their diagnosis is appreciated and to ensure aggressive management and long-term monitoring." (PMID 31044288, 2020). "In addition, like COL4A5 coding type IV collagen, COL4A3 traditionally causes autosomal dominant Alport syndrome and is reported to change susceptibility to diabetic kidney disease." (PMID 32543079, 2020). "In addition, multiple studies have shown that patients with FSGS were reclassified as Alport syndrome based on mutations found in COL4A3, COL4A4, and COL4A5." (PMID 31921302, 2019). "Alport syndrome (AS) is a hereditary condition with considerable genotypic and phenotypic variability, caused by variants in genes encoding collagen type IV chains 3, 4, and 5 (COL4A3–5)." (PMID 31477057, 2019). "Alport syndrome results from mutations in the COL4A5 (X-linked) or COL4A3/COL4A4 (recessive) genes." (PMID 27627812, 2016). "In particular, mutations in the type IV collagen α5 chain gene (COL4A5) are responsible for the X-linked form of the disease, which accounts for ~85% of the patients and mutations in the type IV collagen α3 or α4 chain gene (COL4A3 or COL4A4) lead to the autosomal form of the Alport syndrome." (PMID 26555339, 2015). "Alport syndrome is a hereditary glomerulopathy with progressive proteinuria and nephritis caused by defects in the genes encoding α-3, α-4, or α-5 chains of type IV collagen (COL4A3, COL4A4, COL4A5) in the glomerular basement membrane." (PMID 22937108, 2012). "We present a novel finding of a previously unreported c.687 + 1G > T mutation in COL4A3 that disrupts transcription and translation, impairing α3α4α5 (IV) chain formation, altering the integrity of the glomerular basement membrane, causing hereditary Alport syndrome." (PMID 39924725, 2025). "For instance, Alport syndrome (AS) is a progressive hereditary renal disease accompanied by sensorineural hearing loss and ocular abnormalities, caused by the pathogenic variants in the genes of COL4A3, COL4A4, and COL4A5 encoding type IV collagen α3, α4, and α5 chains, respectively." (PMID 36685964, 2022).
Alport syndrome (continued). "Alport syndrome (AS) is a progressive hereditary kidney disease accompanied by sensorineural hearing loss and ocular abnormalities caused by disease-causing mutations in the COL4A3, COL4A4, and COL4A5 genes, which encode type IV collagen α3, α4, and α5 chains, respectively." (PMID 36013122, 2022). "Applicability of WNK1 kinase activity modulation toward treatment of podocyte injury was assessed using primary and immortalized podocyte cell lines developed from control and Col4a3-/- Alport Syndrome model mice." (PMID 41669953, 2026). "Another four patients were diagnosed with Alport syndrome: three of these presented with de novo missense mutations in the COL4A5 gene, and one patient had a mutation in the COL4A3 gene." (PMID 41828581, 2026). "The rarest form is autosomal dominant Alport syndrome (ADAS), which accounts for about 5% of cases and can be caused by a single inherited copy of a mutated COL4A3 or COL4A4 gene." (PMID 40790091, 2025). "Among the most significant findings, COL4A3 and COL4A5 mutations were the most frequently detected, underscoring Alport Syndrome as the predominant genetic kidney disorder in this cohort." (PMID 41288877, 2025). "The syndrome is caused by mutations in type IV collagen genes (COL4A3, COL4A4, or COL4A5), with X-linked Alport syndrome (XLAS) accounting for approximately 80% of cases." (PMID 40852417, 2025). "It provides the disease confirmation or exclusion, identification of atypical Alport syndrome, determination of symptomatic and asymptomatic monoallelic COL4A3, COL4A4, and COL4A5 carriers (especially COL4A5 females), and inheritance pattern establishment." (PMID 40004525, 2025). "The other cases result from mutations in the COL4A3 or COL4A4 genes, which cause autosomal recessive Alport syndrome (ARAS) and autosomal dominant Alport syndrome (ADAS)." (PMID 40406358, 2025). "Pathogenic variants in COL4A3 and COL4A4 cause autosomal forms of Alport syndrome (autosomal dominant or recessive), while pathogenic variants in COL4A5 cause X‐linked Alport syndrome." (PMID 40317772, 2025). "A dual-plasmid CRISPR-Cas9 system has been developed to correct pathogenic variants in the COL4A3 and COL4A5 genes associated with Alport syndrome." (PMID 40790091, 2025). "Pathogenic variants in type IV collagen genes (COL4A3, COL4A4, COL4A5) are classically associated with Alport syndrome (AS), a hereditary nephropathy primarily affecting the glomerular basement membrane (GBM)." (PMID 40565535, 2025). "A recent study demonstrated that a monoclonal antibody, LTBP-49247, which binds selectively to TGF-β1 in latent complex with LTBPs, reduces renal fibrosis in Col4a3-null mouse model of Alport syndrome and the rat adenine model of kidney disease." (PMID 39990662, 2025). "Alport syndrome is an inherited kidney disease leading to ESKD and is caused by the pathogenic variants of COL4A3/4/5, which encode type IV collagen." (PMID 41426028, 2025). "In Alport syndrome, disruption of the GBM caused by variants in COL4A3, COL4A4, or COL4A5 causes podocyte dysfunction and proteinuria, proliferation of Bowman’s epithelial cells, and progressive glomerulosclerosis." (PMID 40527586, 2025). "Currently, the most accurate method for diagnosing Alport syndrome is comprehensive parallel genetic testing of the entire coding sequences of the COL4A3, COL4A4, and COL4A5 genes using next-generation sequencing (NGS)." (PMID 40004525, 2025). "The other 7 positive tests included amyloidosis (TTR, N = 3), Alport syndrome (COL4A3, N = 2), polycystic kidney disease (PKD1, N = 1), and susceptibility to ESRD (APOL1, N = 1)." (PMID 40126616, 2025). "Alterations in the COL4A3, COL4A4 and COL4A5 genes are associated with glomerular basement membrane-related diseases, such as autosomal recessive Alport syndrome, familial focal segmental glomerulosclerosis, and thin basement membrane nephropathy." (PMID 40351420, 2025).